CXCL10 (C-X-C motif chemokine ligand 10)
Diseases named in the same sentence as CXCL10 in open-access papers (continued):
Sharing a sentence is not in itself a finding about the gene and the disease.
tumor (continued). "Flow cytometric analysis of tumor tissue revealed that both the CXCL10 OE and CCL20 OE groups had a large number of immune cell infiltrates, while the empty vector-transfected 5-8F group lacked the ability to induce immune cell infiltration." (PMID 41399390, 2026). "In vitro, AGO1 knockdown in mouse ECs co-cultured with E0771 tumor cells led to higher levels of Cxcl10 and Vcam1 expression, suggesting a pro-inflammatory and leukocyte-recruiting effect." (PMID 42286210, 2026). "We show that, in the context of chemo-immunotherapy, IL-1β enhances anti-tumor immunity by inducing tumor-cell CXCL10 expression and recruiting CD8+ T cells, thereby sensitizing "cold" tumors to treatment." (PMID 41694383, 2026). "The CXCL10+ macrophage phenotype was most enriched near these Tfh cells, even as distance from tumor boundaries increased, suggesting spatially coordinated cross-talk between these populations." (PMID 41542042, 2026). "CXCL10 promotes anti-tumor immunity by chemotactically attracting effector immune cells, while CCL20 likely recruits Tregs, inhibiting the function of effector immune cells." (PMID 41399390, 2026). "When tumor cells highly expressed CXCL10 but lowly expressed CCL20, there was a significant infiltration of CD8+ T cells and CD20+B cells, but no Treg cell infiltration." (PMID 41399390, 2026). "This is consistent with CXCR3’s established role in guiding T cell trafficking and with CXCR3+ T cells being recruited to CXCL10-rich tumor sites to augment antitumor immunity." (PMID 41129238, 2026). "Genetic silencing of Cxcl10 in dormant cells or pharmacological blockade of CXCR3 in vivo led to early tumor onset and rapid growth in immunocompetent mice." (PMID 41617729, 2026). "In this study, high-throughput sequencing was employed to analyze cytokines secreted by NPC tumor cells, revealing CXCL10, which promotes immune responses, and CCL20, which mediates immune suppression." (PMID 41399390, 2026). "CXCL9 and CXCL10 can be produced by antigen-presenting cells, such as dendritic cells or macrophages, as well as by tumor cells." (PMID 41399390, 2026). "The expression of CD86 and CD206 as well as M2/M1 index were detected by FCM to identify TAM phenotype, while cytokines related to macrophage activation, including IL-6, TNF-α, and CXCL10, were determined in tumor tissue and serum after treatment." (PMID 39744236, 2025). "Regorafenib treatment increases tumor infiltration of CD8+CXCR3+ T cells and inhibits tumor growth by upregulating C-X-C motif chemokine ligand 10 (CXCL10) expression in HCC cells, thereby improving survival rates." (PMID 40317077, 2025). "Cxcl9 and Cxcl10 were specifically expressed in the Tumor-3 subcluster in the young, but much lower expressed in old." (PMID 41332581, 2025). "MSC-sourced CXCL10 (IP-10) facilitates NK cell recruitment into the tumor microenvironment and supports NKG2D expression through CXCR3-mediated activation." (PMID 40643499, 2025). "Clinical trial NCT04830592 uses intravenous infusion to deliver an adenoviral vector producing a bispecific T cell activator (TAc) plus CXCL9/CXCL10/IFNa2 to kill tumor cells and stimulate immunity against the tumor cells." (PMID 41332581, 2025). "If this variant is present in the older TM group, then the up-regulation of CXCL10 would have tumor suppressor actions." (PMID 40149853, 2025). "These cytokines, including CCL5 and CXCL10, up‐regulate tumour cell lysis via large amounts of granzyme B.40, 41Collectively, the activation of the classical pathway results in immunosuppression against tumours." (PMID 41275427, 2025). "CXCL9 and CXCL10 are capable of chemoattracting the lymphocytes leading to the tumor-infiltrating lymphocytes (TILs) phenomena." (PMID 39996769, 2025). "Elevated expression of Cxcr3 and Cxcl10 is compatible with chemokines mediating enhanced CTL recruitment from secondary lymphoid tissues to the tumor site." (PMID 40498983, 2025).
tumor (continued). "Neutrophils also release chemokines, including CXCL3, CXCL8, and CXCL10, which recruit additional immune cells to the tumor site." (PMID 40227814, 2025). "For phagocytes, the changes in the proportions of M1‐differentiated Cxcl10+ and M2‐differentiated Apoe+ macrophages further supported the activation of tumor immunity by 125I@MH therapy." (PMID 40878691, 2025). "On the other hand, the canonical role of CXCL10 is to act as a potent chemoattractant for anti-tumor immune cells, including activated T cells and natural killer (NK) cells, via its receptor CXCR3 within the TME." (PMID 41516196, 2025). "For example, the imbalance between chemokine receptor CXCR3 expressed by TILs that traffic CTL to the TME and CXCL9/CXCL10 (ligands of CXCR3) up-regulated by tumor cells leads to inefficient recruitment of CTL to the tumor." (PMID 40292310, 2025). "This study demonstrates that Piezo1 activation enhances FAK‐YAP‐mediated upregulation of PD‐L1 and CXCL10, thereby promoting an immunotherapy‐responsive tumor microenvironment in NSCLC." (PMID 40583158, 2025). "In vivo analysis in mice showed that the administration of E7766 produced a highly effective anti-tumor response, characterized by infiltrating granulocytes, DCs, B cells, NK cells, and T cells, along with the production of IFNβ and CXCL10 (IP-10)." (PMID 41009575, 2025). "To better understand the relationships between CCL23 and CXCL10 expression on patient survival, we performed an in silico assessment of patient outcomes based on the tumor expression levels using datasets hosted in the Cancer Genome Atlas (TCGA) database." (PMID 41463176, 2025). "M1-polarized TAMs, particularly in HGSOC, secrete CXCL10 in response to IFNγ signaling, which attracts T-cells into the tumor microenvironment." (PMID 40330466, 2025). "Reverse transcription quantitative PCR (RT-qPCR) analysis of tumor tissues unveiled a significant upregulation of several immune-related genes, including Ifng, Gzmb, Cxcl9 and Cxcl10." (PMID 40343532, 2025). "Additional investigation is required to elucidate the impact of CXCL10 on advancing or impeding the development of particular tumor varieties." (PMID 40129528, 2025). "ISGs expressed by some tumour‐associated cDC1s include CXCL9 and CXCL10, which are important for the recruitment and localisation of CD8+ T cells." (PMID 40745918, 2025). "In general, chemokines such as CCL2, CCL4, and CXCL10 can recruit cytotoxic T lymphocytes (CTLs) to the tumor and thus promote the anti‐tumor response." (PMID 40145607, 2025). "A key downstream effector, the chemokine CXCL10, recruits T and NK cells to promote tumor infiltration and influence treatment outcomes." (PMID 41476984, 2025). "This synergism appears to be functionally dependent on the action of chemokines such as CXCL10, which promote a functional anti-tumour immune response through T-cell recruitment and activation." (PMID 39862711, 2025). "Despite this, considering known functions of CXCL9 and CXCL10, maintenance of high levels of these chemokines in tumor cells or TAMs lead to a greater abundance of effector T-cells associated with diseased tissues." (PMID 40176808, 2025). "CXCL10 potentiates the immune response against tumors and reduces tumor growth and metastasis, mainly by regulating immune cell migration and activation." (PMID 41376630, 2025). "CXCL10 also plays a central role in enhancing Th1-like immune responses by attracting Th1 cells and CTLs, which are critical for effective tumor cell killing." (PMID 40760734, 2025). "CXCL10 has been shown to be secreted by various cell types including macrophages, endothelial cells, fibroblasts and tumor cells." (PMID 41376630, 2025).
tumor (continued). "TTFields enhance the effectiveness of anti-PD immunotherapy by improving CD4+ T cells and CD8+ T infiltration via inducing ICD to increase CCL2/8 and CXCL9/CXCL10 expression of tumor cells." (PMID 40098106, 2025). "Higher levels of CXCL10, IL-9, and CCL4 in the tumor tissues were found to be associated with higher numbers of T cells in direct contact with tumor cells." (PMID 40497965, 2025). "Some studies have demonstrated that CXCL10 contributes to the generation of a “hot” tumor, supporting tumor development by drawing tumor cells to establish metastasis." (PMID 40063597, 2025). "In Caglar's breast cancer mouse model, blockade ADORs elevated IFN-γ-induced CXCL10 levels, promoted T lymphocyte recruitment, and suppressed tumor growth." (PMID 40303336, 2025). "Innate immune cells, such as mature dendritic cells and M1-tumor-associated macrophages (TAM), produce cytokines (IFN-α, IL-12, IL-18, or TNF-α) and chemokines (CXCL9, CXCL10, or CCL21) that suppress tumor angiogenesis." (PMID 41373757, 2025). "Beyond tumor cell–intrinsic signaling, CXCL10 exerts potent paracrine effects within the TME, largely mediated by myeloid populations." (PMID 41516196, 2025). "Treatment led to a robust anti-tumor response, characterized by pro-inflammatory mediators such as IFNα, IFNγ, CXCL10, TNFα, and IL-6." (PMID 41009575, 2025). "In SCLC, combining PARP inhibition with radiotherapy elevates the levels of chemokines such as CCL5 and CXCL10, effectively turning an “immune desert” tumor into an “immune-enriched” tumor that is more receptive to PD-1/PD-L1 blockade." (PMID 41194225, 2025). "Functional validation in vitro and in vivo confirms that tumour-intrinsic CXCL10 expression enhances CAR T cell infiltration and improves tumour control." (PMID 41366257, 2025). "Mechanistically, CXCL10 from the stroma activates CXCR3 on tumor cells and stimulates downstream signaling pathways such as MAPK/ERK and PI3K/Akt, leading to cytoskeletal reorganization, enhanced cell survival and targeted migration." (PMID 40760734, 2025). "CXCL10 stimulates immune cells by polarizing and activating T helper cell 1, allowing them to enter tumor tissue and exert phagocytic effects." (PMID 40129528, 2025). "We found that THP1-derived macrophages (THP1-MΦ) cocultured with IFN-β–treated USP5-deficient tumor cells exhibited upregulated ISG15, IFI44, CXCL9, and CXCL10 mRNA expression." (PMID 41321309, 2025). "In summary, our study describes a novel interaction between CCL23 and CXCL10 in the tumor microenvironment, which is also associated clinical findings, indicating reduced overall survival with higher CCL23 and lower CXCL10 levels in human ovarian ascites." (PMID 41463176, 2025). "Preclinical studies demonstrate that EZH2 inhibitors, tazemetostat and valemetostat, upregulate antigen HLA class I/II presentation machinery, OX40L, CD80 co-stimulatory ligands, and T cell-attracting chemokines, CXCL9 and CXCL10 in tumor cells." (PMID 41029427, 2025). "Multiple studies have confirmed that bacterial OMVs can accurately target tumor sites and accumulate, thereby inducing the expression of anti-tumor cytokines such as CXCL10 and interferon-γ." (PMID 41322140, 2025). "CXCL10, as an essential chemokine, directly or indirectly affects tumor growth and metastasis by regulating the differentiation and migration of immune cells." (PMID 40129528, 2025). "In the tumor immune microenvironment, cCCT2-overexpressing senTCs exhibit a senescence-associated secretory phenotype (SASP) with preferential secretion of CXCL10, which induces chemotaxis of CD8+ T-cells." (PMID 40686389, 2025).
tumor (continued). "It is intriguing that Cxcl9 emerged as one of the most downregulated genes in tumor cells from both GeoMx and snRNA-seq, indicating a potential critical role of Cxcl9 and Cxcl10 in the observed phenotypes." (PMID 41332581, 2025). "To learn more about how much cytokine and chemokine levels varied in different tumor compartments depending on the T cell infiltration, we grouped the data of the top four proteins, IL-9, CXCL10, CCL4, and VEGF, median-based into high and low." (PMID 40497965, 2025). "Citrullination of CXCL10 by Peptidyl Arginine Deiminase (PAD) reduces the chemotactic activity of T lymphocytes helping tumours evade immune surveillance." (PMID 40852716, 2025). "IP‐10 (CXCL10) regulates the chemotaxis of T cells to the tumor site, enhancing their differentiation and activation, thus exerting anti‐tumor effects." (PMID 39712456, 2025). "According to our sequencing data and TCGA database, CXCL10 and CXCR3 gene expression was strongly associated with favourable prognosis and the abundance of tumour‐infiltrating CD8+ T cell populations." (PMID 39219056, 2025). "It is reported that the IFNα treatment for cancer cells stimulates CXCL10 secretion, which recruits effector T cells to the tumor microenvironment." (PMID 40243928, 2025). "The inclusion of CXCR4E was intended to block the suppressive pathway driven by cancer-associated fibroblast secretion of CXCL12, which binds CXCR4 on T cells to hinder their tumor engagement and dampen responsiveness to CXCL10." (PMID 41294574, 2025). "This activation leads to the production of CXCL10 by tumor cells, which subsequently facilitates T-cell activation and migration toward the tumor, thereby augmenting anti-tumor immunity." (PMID 41368644, 2025). "The antitumor effect of IL-17 is synergistic with that of IFN-γ, which stimulates tumor cells to release the chemokines CXCL9 and CXCL10 to recruit NKs and CTLs into tumor sites." (PMID 40008144, 2025). "The main goal of CXCL10 ‎gene therapy is to restore or upregulate the expression of CXCL-10 ‎in ‎cancer cells or in the tumor microenvironment, thereby improving immune ‎surveillance and an‎ti tumor response while inhibiting tumor progression." (PMID 40760734, 2025). "Evaluation of macrophage activating cytokines showed that GB2 treatment indeed led to a significant upregulation of IL-6, TNF-α, and CXCL10 both in tumor and serum." (PMID 39744236, 2025). "In reverse, TAMCs-derived CXCL10 reversely promoted tumor epithelial-mesenchymal transition and induced immunosuppressive tumor microenvironment by recruiting CXCR3+ Tregs." (PMID 39965084, 2025). "The concentration of CXCL10 in supernatants from IFNγRKO tumours was slightly lower than in WT tumours." (PMID 39746898, 2025). "The resulting immune desert allows the primary tumor to thrive unchecked while continuing to shed metastatic cells, providing a mechanistic explanation for why high circulating CXCL10 is a robust predictor of poor survival." (PMID 41516196, 2025). "Post‐treatment tumor tissues were analyzed by isolating cells using flow cytometry and measuring the mRNA expression levels of IFNβ1 and CXCL10 to assess their activity." (PMID 39976106, 2025). "Previous studies have reported that HDAC inhibitors can modulate the tumor microenvironment by upregulating chemokines such as CXCL10 and CXCL12, thereby enhancing immune cell infiltration 35,36." (PMID 41049003, 2025). "This study confirms that SFV increases the expression of T-cell chemoattractant genes Cxcl9, Cxcl10, Cxcl11 and immune checkpoint molecule gene Cd40, promoting anti-tumour immunity." (PMID 40547518, 2025). "Current evidence suggests that CXCL10’s functional effects depend on spatiotemporal context—including local versus systemic concentration, cellular source (tumor versus stromal), and the specific CXCR3 receptor isoforms expressed." (PMID 41516196, 2025).
tumor (continued). "Proinflammatory chemokines typically produced by DCs to promote the recruitment of T cells, such as CCL5, CXCL9, and CXCL10, were increased in the tumor microenvironment of mice treated with the combination." (PMID 40578365, 2025). "These genes included key immune modulators, such as Cxcl9 and Cxcl10, responsible for recruiting CD8+ T cells, and H2-K1 and H2-D1, encoding MHC class I (MHC-I) genes crucial for antigen presentation and thus tumor recognition by CD8+ T cells." (PMID 39540840, 2025). "It secretes a plethora of pro-inflammatory cytokines and chemokines, including IL-1β, IL-12, IL-23, IFN-γ, TNF-α, CCL2, and CXCL10, which are pivotal in amplifying the infiltration of anti-tumor immune cells and in the elimination of cancer cells." (PMID 41219968, 2025). "In sum, we conclude the suppression of Cxcl9 and Cxcl10 in old tumors drives decreased infiltration of anti-tumor T cells and faster growth of the tumor." (PMID 41332581, 2025). "This enhances the immune response against the tumor, as CXCL10 helps to recruit and activate CD3+ T-cells, facilitating a coordinated attack on cancer cells." (PMID 40330466, 2025). "The IFNβ downstream chemokines CCL5 and CXCL10 are important for the recruitment of immune cells into the tumor microenvironment, driving the antitumor immune response." (PMID 39700406, 2025). "By neutralizing CXCL10, these antibodies can alter the tumor’s immunosuppressive microenvironment and potentially restore immune surveillance." (PMID 40760734, 2025). "We propose that high systemic tumor-derived CXCL10 establishes an immune decoy, misdirecting potent anti-tumor T cells away from the primary tumor." (PMID 41516196, 2025). "First, recruitment and activation of immune cells: for example, a current study has shown that CAR-M-Exosomes not only target tumor cells but also, being rich in the chemokine CXCL10, can effectively recruit T cells and M1-type macrophages." (PMID 40904456, 2025). "The role of CXCL10 in tumor progression is a double-edged sword, and its specific effects depend on various factors, including tumor type, characteristics of tumor microenvironment, and immune system status." (PMID 40129528, 2025). "Uncoupling protein 2 (UCP2) reprograms the TME from immunosuppressive to immunostimulatory by increasing CXCL10 production, attracting T cells to the tumor, and normalizing tumor vasculature, which further improves T cell infiltration." (PMID 40872475, 2025). "The increase in T cells in the TME after aCD40 treatment was possibly due to the increase in the production of chemokines such as CCL5, CCL21, CXCL9, and CXCL10 within the tumor." (PMID 40585246, 2025). "As the disease progresses, elevated systemic levels of CXCL10 overwhelm the localized chemokine gradient at the primary tumor site, creating a potent immune decoy that diverts anti-tumor CXCR3+ T cells away from the tumor." (PMID 41516196, 2025). "CXCL10-expressing tumour-bearing mice showed a significant decrease in peripheral human leukocyte proportions between day 28 and 56, resulting in a potential time bias when comparing both groups at the respective study endpoint." (PMID 41366257, 2025). "Chemokines such as C-C motif chemokine ligand 5 (CCL5), C-C motif chemokine ligand 11 (CCL11), C-X-C motif chemokine ligand 9 (CXCL9), and C-X-C motif chemokine ligand 10 (CXCL10) are believed to be primary mediators of eosinophil-driven tumor necrosis." (PMID 40761780, 2025). "ScRNA-seq analysis revealed elevated expression of Cxcr3, consistent with enhanced tumor-homing capacity, alongside production of Cxcl10, suggesting a chemoattractant role." (PMID 40229241, 2025). "We reported a significant, higher than in 4T1 tumor-bearing mice, 2’3’-cGAMP-induced increase in CXCL10, CCL2, CCL4, TNF-α, IFN-α and IFN-β concentrations." (PMID 39857957, 2025).